PGR (progesterone receptor)
Diseases named in the same sentence as PGR in open-access papers (continued):
Sharing a sentence is not in itself a finding about the gene and the disease.
breast cancer (continued). "Triple negative breast cancer (TNBC) accounts for ~15–20% of incident breast cancers and is characterized by negativity for estrogen receptor (ER), progesterone receptor (PR), and human epidermal growth factor receptor 2 (HER2)." (PMID 36351947, 2022). "Historical breast cancer classification is largely based on the cancer driver activity of ERα along with other hormone receptors, progesterone receptor (PR) and receptor tyrosine kinase HER2/ERBB2." (PMID 34497382, 2022). "For instance, in breast cancers, the expression status of estrogen receptor α (ERα), progesterone receptor (PR), and human epidermal growth factor receptor 2 (HER2) can be used to guide treatment decisions." (PMID 35053220, 2022). "AKT reduces PGR protein expression levels in breast cancer cells, EEC cells, and endometriotic stromal cells." (PMID 36498921, 2022). "Approximately 70% of all breast cancers are hormone-dependent and express estrogen receptor α (ERα) and progesterone receptor (PR)." (PMID 36009407, 2022). "Hormone receptor (HR)-positive breast cancers, including estrogen receptor (ER)- and/or progesterone receptor (PR)-positive breast cancers, account for more than 70% of all breast cancer cases and lead to approximately 50% of breast cancer-induced deaths." (PMID 36209184, 2022). "Luminal A breast cancer is categorized by a lower expression of estrogen receptor (ER) and progesterone receptor (PR) and a high histologic grade with better overall survival and disease-free survival." (PMID 36009373, 2022). "Breast cancer accounts for 11.7% of all cancer cases, and several valuable markers have been advocated, such as estrogen receptor (ER), progesterone receptor (PR), human epidermal growth factor receptor 2 (HER2), and Ki67." (PMID 35326237, 2022). "Triple-negative breast cancer (TNBC) is an aggressive breast cancer subtype which lacks the estrogen receptor (ER) and progesterone receptor (PR) expression and also lacks overexpression of the human epidermal growth factor receptor 2 (HER2)." (PMID 36145265, 2022). "Triple-negative breast cancer (TNBC), a subtype of breast cancer, has been clinically characterized by the insufficient expression of estrogen receptor, progesterone receptor, and HER2." (PMID 35216272, 2022). "Determination of hormone receptor status, both the ER and the PgR, in breast cancer is standard of care, as the receptor status has both prognostic implications and dictates therapy." (PMID 35729608, 2022). "The algorithm, based on ResNet50, was trained using a multi-country dataset of 3474 patients (Australian Breast Cancer Tissue Bank and The Cancer Genome Atlas), and achieved AUCs of 0.92, 0.81, and 0.78, for ER, PgR, and HER2, respectively." (PMID 36005456, 2022). "Breast cancer (BC) has three main types: the luminal BC, which is estrogen and/or progesterone receptor positive; the human epidermal growth factor 2 (HER-2)-positive BC; and the triple negative BC, which lacks the expression of these receptors." (PMID 35453610, 2022). "According to the level of estrogen receptor (ER), progesterone receptor (PR), and human epidermal growth factor 2 (Her2), breast cancers are classified into multiple subtypes: Luminal, Her2 overexpression, Basal-like, and Normal-like." (PMID 36572949, 2022). "Triple-negative breast cancer (TNBC) is a subtype of breast cancer that lacks estrogen receptor (ER), progesterone receptor (PR), and human epidermal growth factor receptor 2 (HER2) expression." (PMID 35454764, 2022). "Triple-negative breast cancer (TNBC) is a type of breast cancer that exhibits low expression of estrogen receptor (ER), progesterone receptor (PgR), and human epidermal growth factor receptor-2 (HER2)." (PMID 36341391, 2022). "Molecular subtypes and optimal treatments for breast cancer are usually based on immunohistochemical markers such as estrogen receptor (ER), progesterone receptor (PR), and human epidermal growth factor receptor 2 (HER2)." (PMID 36276273, 2022).
breast cancer (continued). "The novel findings of this study lay in that the ER−/PgR + tumor tended to present an inferior prognosis, even to that of ER−/PgR− subtype breast cancer." (PMID 35041101, 2022). "Therapeutic decisions in breast cancer (BC) are, among other factors, based on the expression of the predictive markers on the primary tumor (PT): the estrogen-(ER) and progesterone receptor (PR) as well as the epidermal growth factor receptor HER2." (PMID 35025065, 2022). "The most common IHC breast cancer prognostic markers are the hormonal receptors, comprising the estrogen receptor (ER) and the progesterone receptor (PgR), the human epidermal growth factor receptor-2 (HER2), and the cellular marker for proliferation ki67." (PMID 35565344, 2022). "Breast cancers can be classified according to stage, pathology, grade, and expression of estrogen receptor (ER), progesterone receptor (PR), or human epidermal growth factor receptor (Her2/neu)." (PMID 35684200, 2022). "Traditionally, four different subtypes of breast cancer have been identified based on the expression of three molecules: the oestrogen receptor (ER), the progesterone receptor (PR) and the human epidermal growth factor receptor 2 (HER2)." (PMID 35150062, 2022). "Indications for endocrine therapy for breast cancer are estrogen receptor (ER) and/or progesterone receptor positivity." (PMID 36294896, 2022). "Triple-negative breast cancer (TNBC) is a subtype of breast cancer (BC) that lacks the immunohistochemical expression of the estrogen receptor (ER), the progesterone receptor (PR), and the human epidermal growth factor receptor-2 (HER-2)." (PMID 36009390, 2022). "Triple-negative breast cancer (TNBC) accounts for 10–20% of primary breast cancers that lack expression of estrogen receptor (ER), progesterone receptor (PR), and human epidermal growth factor receptor 2 (HER2)." (PMID 35681552, 2022). "Breast cancers are categorized into subtypes based on hormone receptors (HR), namely estrogen receptor (ER) and progesterone receptor (PR), and human epidermal growth factor receptor 2 (HER2) expression status." (PMID 35401937, 2022). "The estrogen receptor (ER) and progesterone receptor (PR) steroid receptors were the first biomarkers classified in breast cancer." (PMID 35406430, 2022). "In contrast, MCF-7 cells (luminal A breast cancer subtype cell line, estrogen and progesterone receptor-positive, HER2-negative) generate ATP primarily through oxidative phosphorylation." (PMID 36365190, 2022). "Breast cancer is a highly heterogenous disease which is classified in several subtypes based on the expression of estrogen receptor-α (ERα), progesterone receptor (PR) and epidermal growth factor receptor 2 (HER2), among other characteristics." (PMID 36497283, 2022). "ER-positive breast cancers are significantly more likely to be AR-positive than ER-negative tumours, with some studies suggesting AR status is a correlate of ER-alpha/PgR signaling." (PMID 35512428, 2022). "Triple Negative Breast Cancer (TNBC), a subtype of breast cancer, lacks expression of the oestrogen receptor, progesterone receptor, and HER2." (PMID 36909691, 2022). "The subtypes of breast cancer are based on the expressions of estrogen receptor (ER), progesterone receptor (PR) and human epidermal growth factor 2 (HER-2)." (PMID 36699456, 2022). "Breast cancer is heterogeneous and is characterised by the expression of oestrogen receptor α (ER), progesterone receptor (PR) and human epidermal growth factor receptor 2 (HER2)." (PMID 36293165, 2022). "In ER+/progesterone receptor (PR)+ early breast cancer, AQP5 overexpression is a potential prognostic marker of patient survival." (PMID 36212456, 2022). "The classification of breast cancer based on the expression of estrogen receptor/progesterone receptor, over expression and gene amplification of Her-2 gene." (PMID 36685962, 2022).
breast cancer (continued). "In clinical practice, breast cancer classification into subtypes is performed estimating the expression of main IHC prognostic markers, such as ER, PgR, HER2, and ki67, in cancer cells." (PMID 35565344, 2022). "As the mainstay consideration for breast cancer subtypes, the steroid hormone receptors ER and PgR are two critical biomarkers for assessing the intrinsic heterogeneity and introducing multidisciplinary therapeutics." (PMID 35041101, 2022). "Breast cancer is divided into four types based on the expression of Estrogen Receptor (ER), Progesterone Receptor (PR), Human Epidermal Growth Factor (HER2), and Ki-67: Luminal A, Luminal B, HER2-Enriched and Three Breast Cancer Negative (TNBC)." (PMID 36213818, 2022). "Over 80% of all breast cancer cases are deemed ER-positive and/or progesterone receptor (PgR)-positive, and oestrogen is the primary growth stimulant of these tumours." (PMID 35613334, 2022). "Molecular subtypes of breast cancer were defined using immunohistochemistry (IHC) tumour markers, oestrogen receptor (ER), progesterone receptor (PR), human epidermal growth factor receptor-2 (HER2), and tumour grade." (PMID 36116093, 2022). "The major categorization of breast cancer is based upon the expression pattern of immuno-molecular markers such as estrogen receptor or ER, progesterone receptor or PR, and human epidermal growth factor receptor 2 (HER2)." (PMID 36276982, 2022). "In triple-negative breast cancer, IGF2BP3 and IGF2BP2 synergistically recruited CNOT1 complex, reduced the stability of progesterone receptor and ultimately promoted the migration and metastasis of breast cancer." (PMID 35676262, 2022). "In the routine practice, ER−/PgR + subtype breast cancer was considered as endocrine-related and would receive endocrine therapy and chemotherapy of which the protocol was with moderate strength given the estimated favorable prognosis." (PMID 35041101, 2022). "Progesterone and progesterone receptor (PR) can promote the progression of breast cancer, whereas the effect of progesterone is protective against the development of estrogen-driven EC." (PMID 35743699, 2022). "Of the breast cancer patients, 76 (75.2%) had estrogen receptor, 57 (56.4%) had progesterone receptor, and 29 (28.7) had HER2 (28.7%)." (PMID 35008418, 2022). "Clinical characteristics including estrogen receptor (ER), progesterone receptor (PR), and human epidermal growth factor 2 (HER2) are important biomarkers in the treatment of breast cancer, but how genomic mutations affect their status is rarely studied." (PMID 35494043, 2022). "For years, breast cancer treatment has been led by tissue-based biomarkers, like estrogen receptor, progesterone receptor and HER2 status." (PMID 35818030, 2022). "The estrogen receptor (ER) and progesterone receptor (PR) are expressed in more than 75% of breast cancers." (PMID 35711896, 2022). "Breast cancer endocrine therapy is actually related to the expression of the steroid hormones, estrogen receptor (ER), and progesterone receptor (PR)." (PMID 35711896, 2022). "Most breast cancer diagnoses occur in postmenopausal women and three-quarters are estrogen receptor alpha (ER) and usually progesterone receptor (PR) positive." (PMID 35406548, 2022). "For breast cancer, we examined the status of the estrogen receptor (ER), progesterone receptor (PR), and human epidermal growth factor receptor 2 (HER2)." (PMID 35493488, 2022). "This case–control study encompassed positive estrogen and/or progesterone receptor, stage 1–3 breast cancer female patients receiving tamoxifen at Al-Bairouni University Hospital, the major National Oncology Center in Syria." (PMID 36243690, 2022). "Approximately 80% of all breast cancer cases are classified as estrogen receptor (ER) positive, and of these 65% are concurrently progesterone receptor (PR) positive." (PMID 35735435, 2022).
breast cancer (continued). "Patients with primary breast cancer and centrally confirmed ER, PgR, and HER2 status were enrolled in the randomized prospectively conducted phase III GeparTrio trial." (PMID 36195836, 2022). "TET2 p.Ala304Val has only been previously identified in melanoma, while TET2 p.Phe868Leu has been previously identified in estrogen- and progesterone-receptor positive breast cancer, adult T cell lymphoma/leukaemia, and MDS." (PMID 35033063, 2022). "Estrogen and progesterone receptor status can predict breast cancer patient prognosis and treatment sensitivity, but research on low ER and PR levels and expression balance remains limited." (PMID 36531979, 2022). "The expression of estrogen receptor α (ERα) and progesterone receptor (PR) in canine mammary tumors has been postulated as one important characteristic to support the use of the canine model." (PMID 36006309, 2022). "miR-129-2-mediated downregulation of progesterone receptor has been shown in breast cancer cells in response to progesterone." (PMID 36362173, 2022). "Breast cancer is a heterogeneous disease, with major subtypes defined by expression of estrogen receptor (ER), progesterone receptor (PR), and epidermal growth factor receptor 2 (HER2) receptor." (PMID 35251975, 2022). "Currently, breast cancer is classified into different molecular subtypes based on molecular markers for estrogen receptor (ER), progesterone receptor (PR), and human epidermal growth factor receptor 2 (HER2)." (PMID 36479102, 2022). "Approximately three-quarters of all breast cancer patients have estrogen and/or progesterone receptor positivity." (PMID 35677000, 2022). "In progesterone receptor-negative breast cancer patients, the expression level of UBE2V2 and UBE2A was higher than in patients with progesterone receptor-positive breast cancer." (PMID 36713553, 2022). "By contrast, when the effects of NACT are evaluated in estrogen receptor (ER)/progesterone receptor (PR)-positive breast cancer patients only, CD8+TILs are depleted post-NACT." (PMID 36139665, 2022). "Hormone receptors (HR), consisting of ER and PgR, are critical markers for treatment introduction of breast cancer." (PMID 35041101, 2022). "Clinically, breast cancer is routinely categorized into four molecular subtypes according to the presence of estrogen receptor (ER), progesterone receptor (PR) and human epidermal growth factor (HER2)." (PMID 34882895, 2022). "Three major subtypes characterize most breast cancer cells, i.e., estrogen receptor (ER), progesterone receptor (PR), and human epidermal growth factor receptor 2 (HER2)." (PMID 36559026, 2022). "Here, SETD7-mediated methylation of K302 on ER ensures protein stability and promotes DNA binding activity and the expression of ER-downstream genes, such as PS2 and progesterone receptor (PgR), in breast cancer." (PMID 35812730, 2022). "Breast cancer patients with positive progesterone receptor and human epidermal growth factor receptor-2 showed an increased level of INHBA mRNA expression." (PMID 36304286, 2022). "Triple-negative breast cancer (TNBC) occurs in about 10 to 20% of diagnosed breast cancers and defined by the absence or minimal expression of estrogen receptor (ER), progesterone receptor (PR) and epidermal growth factor receptor 2 (HER2)." (PMID 36497286, 2022). "Breast cancer is a highly heterogeneous tumor that is currently classified by three molecular markers, including estrogen receptor (ER), progesterone receptor (PR) and HER2 (also called ERBB2)." (PMID 35387130, 2022). "ER and/or Progesterone Receptor (PR)‐status are important biomarkers in breast cancers and, at present, defined clinically as the presence of at least 1% positive staining in tumor nuclei through Immuno‐Histo‐Chemistry (IHC) testing." (PMID 34086424, 2022).
breast cancer (continued). "The primary classification of breast cancer is based on immunohistochemistry markers in tumor biopsies: estrogen receptor (ER), progesterone receptor (PR), KI-67, and human epidermal growth factor 2 (HER2)." (PMID 35053474, 2022). "The updated 2020 ASCO/CAP Guidelines for Estrogen and Progesterone Receptor Testing in Breast Cancer suggest retesting ER in cases of highly unusual ER‐negative or ER‐positive results." (PMID 35733293, 2022). "miR-17 expression correlates with breast cancer stage, estrogen and progesterone receptor and lymph node status, and its upregulation promotes breast cancer migration and invasion." (PMID 35625825, 2022). "Approximately two thirds of primary breast cancers express the PgR, and the majority of these are also ER-positive." (PMID 35729608, 2022). "As we know, estrogen-controlled progesterone receptor (PR) synthesis was mediated by ER; thus, PR was always used as a marker of estrogen activity in breast cancer." (PMID 36233194, 2022). "Clinically, breast cancers are categorized into three major groups, and established from estrogen receptor (ER), progesterone receptor (PR), and human epidermal growth factor receptor 2 (HER2) expression." (PMID 35884530, 2022). "The most common breast cancer subtype is hormone receptor positive, expressing the ER and/or progesterone receptor, accounting for approximately 75% of breast cancers." (PMID 36686845, 2022). "More than 2/3 of breast cancers are estrogen receptor (ER) positive and/or progesterone receptor (PR),and hormone-dependent breast cancer women are sensitive to endocrine therapy drugs." (PMID 35477451, 2022). "Molecular classification of breast cancer into subtypes based on expression of estrogen receptor (ER), progesterone receptor (PR), and human epidermal growth factor receptor 2 (HER2) have provided therapeutic options that have improved clinical outcome." (PMID 35625867, 2022). "Breast cancer subtypes are also classified based on the presence or absence of hormone receptors (HRs), including estrogen receptor (ER) and progesterone receptor (PR)." (PMID 36338541, 2022). "In terms of S100A9/8, Bergenfelz was the first to report that it can be considered as a novel therapeutic target for patients with ER(−) PgR(−) breast cancers followed by several other studies." (PMID 36536459, 2022). "Breast cancer was the most common malignancy in women, of which 70–80% of cases expressed steroid hormone receptors, including estrogen receptor (ER) and progesterone receptor (PR)." (PMID 36232774, 2022). "The classification is based on the expression of breast cancer markers, i.e., oestrogen receptor (ER), progesterone receptor (PR), HER2 and the proliferation marker Ki-67 expressions." (PMID 36556428, 2022). "The molecular types of breast cancer include Ki-67, estrogen receptor (ER), progesterone receptor (PR), and human epidermal growth factor receptor-2 (HER2), which provide diagnostic and prognostic evidence and guidance for treatment." (PMID 35096057, 2022). "Breast cancer is a heterogeneous disease divided into different molecular subtypes according to the expression of biological markers: the estrogen receptor (ER), progesterone receptor (PR) and human epidermal growth factor receptor 2 (HER2)." (PMID 35631334, 2022). "Estrogen-receptor (ER) and progesterone-receptor (PR) expression levels in breast cancer, which have been principally compared via binomial descriptors, can vary widely across tumors." (PMID 35135604, 2022). "Breast cancer is subdivided into immunohistochemistry (IHC) subtypes based on the status of estrogen receptor (ER), progesterone receptor (PR) and human epidermal growth factor receptor II (HER2)." (PMID 36551748, 2022). "As to other cancer types, the NAV1 promoter hypomethylation was observed in hormone receptor positive (expressing the estrogen receptor, ER+ and/or progesterone receptor, PR+) breast cancers which seems to be consistent with our results." (PMID 35867729, 2022).